SCPPPQ1 (secretory calcium-binding phosphoprotein proline-glutamine rich 1 )
Gene: Protein-coding gene on chromosome 4 (87,460,802 to 87,471,050, reverse strand). Ensembl gene ENSG00000272856.
Gene Ontology:
Cellular component: extracellular region
Homologues: Orthologues: rat Scpppq1 (63% identical), mouse Scpppq1 (57% identical).